HDAC8 (histone deacetylase 8)
Diseases named in the same sentence as HDAC8 in open-access papers (continued):
Sharing a sentence is not in itself a finding about the gene and the disease.
neuroblastoma (continued). "Thus, we hypothesize that HDAC8 and ATRA signaling partly converge at the level of CREB and the combined treatment of neuroblastoma cells with HDAC8 inhibitors and retinoic acid enhances differentiation." (PMID 25695609, 2015). "Indeed, both LY294002 and rapamycin significantly enhanced entinostat-mediated effects on cell viability, suggesting that HDAC1–3 inhibitors, but not HDAC8 inhibitors, cooperate with PI3K/mTOR inhibitors in our neuroblastoma MYCN-driven model." (PMID 29515255, 2018).
breast cancer (38 papers, 2010 to 2025). A primary or metastatic malignant neoplasm involving the breast. "High expression of HDAC2 and HDAC8 has been demonstrated to be associated with resistance of breast cancer cells to radiation." (PMID 35193602, 2022). "Overexpression of HDAC8 has been indicated to be associated with poor prognosis and drug resistance in breast cancer[31 ▶]." (PMID 32429642, 2020). "The current study was conducted to evaluate the possible association between HDAC8 expression and clinical outcomes of patients with breast cancer." (PMID 32429642, 2020). "In conclusion, our data indicate the diagnostic value of HDAC8 in breast cancer patients and the results suggest that it could serve as a predictor of breast cancer development." (PMID 32429642, 2020). "The role of HDAC8 in cancer remains largely undefined; studies suggest that the expression of HDAC8 was upregulated in breast cancer tissues as compared to the controls." (PMID 40426890, 2025). "CNP0112925 (arundinin), bearing a polyphenolic structure, was confirmed to inhibit HDAC8 activity and tubulin organization, affecting breast cancer cell viability and triggering mitochondrial superoxide production and apoptosis." (PMID 39594568, 2024). "Further investigations have enlightened that HDAC8 promoted dissemination of breast cancer cells in vitro and in vivo, through the activation of EMT, a central process underlying metastasis." (PMID 36077415, 2022). "Through binding to the 3′-UTR of HDAC8, miR-216b-5p inhibits proliferation and progression in breast cancer cells." (PMID 36467881, 2022). "This idea is supported by the finding that a specific inhibition of HDAC8 with the compound PCI-34051 can delay cell cycle progression of breast cancer cells." (PMID 34665271, 2022). "In the research of new epigenetic targets, HDAC8 exhibited antiproliferative properties in different breast cancer subtypes." (PMID 36077415, 2022). "They revealed the high expression levels of these class I HDACs, and IHC results for HDAC1, HDAC2, HDAC3, and HDAC8 were positive in 17 (85%), 20 (100%), 20 (100%), and 17 (85%) of 20 breast cancer cases, respectively." (PMID 36188615, 2022). "miRNA-216b-5p was decreased within human breast cancer tissues and was correlated with lymph node metastasis and advanced tumor size, which functioned by targeting HDAC8." (PMID 34470640, 2021). "In breast cancer, the oncogene histone deacetylase 8 (HDAC8), which accelerates proliferation and progression, is targeted by miR-216-5p via binding to the 3'UTR." (PMID 32258065, 2020). "Studies have revealed an oncogenic role for HDAC8 in the progression of breast cancer and have indicated the effect of this gene on TNBC." (PMID 32429642, 2020). "It was possible to validate the overexpression of HDAC8 in breast cancer specimens; therefore, it was determined that HDAC8 is higher in TNBC samples than in nTNBC and benign tissue." (PMID 32429642, 2020). "In line with previous studies, the current findings suggested a significant elevation of HDAC8 in breast cancer tissue specimens compared to normal adjacent tissues samples." (PMID 32429642, 2020). "Our results showed that the expression of HDAC8 in breast cancer tissues was significantly higher than the normal adjacent tissues (p = 0.0011)." (PMID 32429642, 2020). "Overexpression of HDAC8 has been found to increase the migration of breast cancer cells through the Hippo signaling pathway." (PMID 32429642, 2020). "A specific role of HDAC8 was also demonstrated in breast cancer, where a selective HDAC8 inhibitor suppressed Notch 1 expression." (PMID 31247937, 2019). "Among 11 Zn2+-dependent HDAC isozymes, HDAC8 was found immunoreactive in 85% of breast cancer patients." (PMID 31817161, 2019). "In this study, we report the characterization of the anti-tumor activity and underlying mechanisms of a novel HDAC8 inhibitor, (E)-N-hydroxy-4-methoxy-2-(3,4-methylenedioxyphenyl)cinnamide (HMC), in breast cancer cells." (PMID 31817161, 2019).
breast cancer (continued). "Together, these findings suggest the potential of using HMC as a scaffold to develop potent HDAC8 inhibitors for breast cancer therapy." (PMID 31817161, 2019). "In the present study, we investigated the antitumor effect of a novel HDAC8-selective inhibitor HMC in breast cancer cells." (PMID 31817161, 2019). "Inhibition of HDAC8 results in α-tubulin acetylation and therefore sensitizes breast cancer cells to tubulin-polymerizing agents." (PMID 23805307, 2013). "HDAC8 is highly expressed in breast cancer compared to other types of cancers." (PMID 40260239, 2025). "Additionally, HDAC8 was shown to drive breast cancer cell dissemination through the AKT/GSK-3β/Snail signaling pathway." (PMID 40260239, 2025). "One of these natural compounds, arundinin, found in Pleione bulbocodioides, Pleione yunnanensis, and other organisms, was demonstrated to significantly inhibit HDAC8 activity and to affect tubulin organization, with effects on mitochondrial superoxide and apoptosis on breast cancer cells." (PMID 39594568, 2024). "With regard to tumours, PHF5A is overexpressed in lung cancer, breast cancer, colorectal cancer and hepatocellular carcinoma and promotes malignant tumour biological progression associated with the NF-κB pathway, RhoA/ROCK pathway, and activation of HDAC8." (PMID 37434235, 2023). "In our study, we found decreased HDAC2 and HDAC8 expression, inhibited HDACs activity, decreased DNMT3b expression, and decreased DNMTs activity, indicating that inulin dietary treatment induced protective epigenetic changes in mammary tumor cells in mice." (PMID 37240357, 2023). "One such histone deacetylase, namely, HDAC8, is implicated in the invasion and metastasis abilities of cancer; meanwhile, selective inhibition of HDAC8 serves as a therapeutic agent in various malignancies, including breast cancer, hepatocellular carcinoma, and CRC." (PMID 36035205, 2022). "Despite the well-recognized roles of HDAC8 in the progression of breast cancer, its diagnostic value has not been considered." (PMID 32429642, 2020). "Previous data have shown the tumorigenicity roles of HDAC8 in breast cancer." (PMID 32429642, 2020). "It was also reported that HDAC8 was required to maintain Notch1 protein stability by protecting against degradation mediated by Fbxw7 in a deacetylase activity-independent manner in breast cancer." (PMID 31362948, 2019). "HDAC8 was suggested to activate breast cancer stem cell-like properties and increase cell invasion." (PMID 27248326, 2016). "HDAC1, HDAC2, and HDAC8 were found to form a complex with EMT-TF Snail and induce EMT in breast cancer cells to promote migration." (PMID 40165290, 2025). "SIRT7 can inhibit metastasis of breast cancer by inhibiting TGF-β signaling, and HDAC8 can suppress the expression of SIRT7 to promote cancer cell survival and migration." (PMID 40165290, 2025). "These include entinostat/MS-275 and NKL54, which favor class I enzymes other than HDAC8, and chidamide/CS055, which has been approved by the China Food and Drug Administration for peripheral T-cell lymphoma and advanced breast cancer." (PMID 39624079, 2024). "Other HDAC8‐selective inhibitors such as 1,3,4‐oxadiazole‐alanine hybrid and BMX also induce cell apoptosis in breast cancer cells and colorectal cancer cells." (PMID 39317961, 2024). "Among the set of compounds, 45 exhibited the highest HDAC8 inhibitory potency (IC50 = 98 nM) and antiproliferative activity against MDA-MB-231 breast cancer cell line (IC50 = 230 nM)." (PMID 36077415, 2022). "Another report found that PCI34051, a histone deacetylase 8 (HDAC8)-specific inhibitor, blocked SMC deacetylation and thus blocked cell cycle progression and cell survival in MCF7 breast cancer cells." (PMID 32518584, 2020). "Further molecular mechanisms of TSA including down-regulation of HDAC8 in colon cancer cell line SW620, HDACs 5 and 8 in lung cancer, breast cancer, and skin cancer cells." (PMID 32711442, 2020).
breast cancer (continued). "They, also, determined that the network of HDAC8 and YY1 prevents the proliferation of breast cancer cells." (PMID 31908740, 2019). "Yet, SAHA can promote migration and EMT via HDAC8/FOXA1 signals in MDA-MB-231 and BT-549 breast cancer cells." (PMID 30691229, 2019). "Moreover, HDAC8, along with isoforms 1 and 6, was proven to increase invasion and MMP9 expression in breast cancer cells, and together with MMP2, is overexpressed in AML and acute lymphoblastic leukaemia (ALL)." (PMID 36077415, 2022). "There are also reports of SAHA promoting EMT through the HDAC8/FOXA1 axis in triple-negative MDA-MB-231 and BT-549 breast cancer cells, in which SAHA upregulated the mesenchymal markers N-cadherin, vimentin, and fibronectin and downregulated E-cadherin expression." (PMID 34502112, 2021). "In breast cancer tissues and cells, HDAC8 expression is up‐regulated, and HDAC8 interacts with AKT1, deacetylating it at lysine 426 and activating AKT1, thereby increasing GSK‐3β phosphorylation and promoting its degradation, which triggers the spread and EMT of breast cancer cells." (PMID 39778006, 2025). "The last member of class I, HDAC8 is absent in colorectal, testis and breast cancer." (PMID 30691229, 2019). "Chrysin was proven to be an HDAC2/8 dual inhibitor (HDAC2 EC50 = 129.0 μM; HDAC8 EC50 = 40.2 μM), without showing any activity on HDAC1, and was able to suppress cell growth while promoting differentiation in human breast cancer MDA-MB-231 cells." (PMID 36077415, 2022).
hepatocellular carcinoma (28 papers, 2017 to 2025). A malignant tumor that arises from hepatocytes. "HDAC8 was associated with the promotion of IR in NAFLD-associated hepatocellular carcinoma (HCC)." (PMID 35087408, 2021). "ZDHHC12 knockdown in hepatocellular carcinoma cells decreased the level of HDAC8 expression, but when HSC70 or LAMP2A was knocked down, HDAC8 was not degraded, with or without ZDHHC12." (PMID 40787880, 2025). "In mouse models of hepatocellular carcinoma, HDAC8 inhibitors can remodel the epigenetic program in tumor cells and effectively restore H3K27 acetylation." (PMID 40013761, 2025). "In conclusion, MPH-5 emerges as a promising dual-targeted MPS1/HDAC8 inhibitor with potential for the treatment of hepatocellular carcinoma." (PMID 39351092, 2024). "As HDAC8 inhibition had an anti-proliferative effect in hepatoma cells, it has been suggested that xenobiotics can alter the epigenetic dynamics by stimulating the AHR-HDAC8 axis and thereby contributing to hepatocarcinogenesis." (PMID 37696456, 2023). "The aberrant overexpression of HDAC8 has been observed in various cancers, such as gastric cancer, hepatocellular carcinoma (HCC), oral squamous cell carcinoma (OSCC), and childhood acute lymphoblastic leukemia (ALL)." (PMID 36831463, 2023). "In a syngeneic and orthotopic C57BL/6 mouse Hepa1-6 hepatoma model, selective HDAC8 inhibitor PCI -34051 combined with anti-PD-L1 therapy improved tumor-infiltrating CD8+ T cells, eliciting an effective and up to 15-month tumor-free response to ICB." (PMID 36685594, 2022). "HDAC8 is a multifaceted target for therapeutic interventions in colon, lung, and hepatocellular carcinoma cervical cancers as well, which regulates proliferation and apoptosis in cancer cells." (PMID 34308568, 2021). "HDAC8 has been reported to promote the proliferation of hepatocellular carcinoma and inhibit apoptosis." (PMID 34880761, 2021). "Another class I HDAC, HDAC8, has been linked to the promotion of IR in NAFLD-associated hepatocellular carcinoma (HCC)." (PMID 34046015, 2021). "AC009495.2 suppresses tumour metastasis by activating the HDAC8/ID2 pathway in hepatocellular carcinoma." (PMID 32887470, 2020). "In our study, specific HDAC8 inhibitors repressed hepatoma cell proliferation and transformation activity via in vitro and in vivo upregulation of RB1." (PMID 29301348, 2018). "The HDAC8 promoter region between −168 and +30 bp was pulled down by the anti-AHR antibody in hepatoma cells with high HDAC8 expression." (PMID 27283490, 2017). "Forced AHR overexpression enhanced mRNA and protein expression of CYP1B1 and HDAC8 in both hepatoma cell lines." (PMID 27283490, 2017). "The hepatoma cells with HDAC8 expression showed a lesser degree of enhancement (30%) of BrdU incorporation than those overexpressing AHR." (PMID 27283490, 2017). "In summary, we demonstrated that AHR regulated cell proliferation and tumorigenesis by directly targeting and activating HDAC8 expression in hepatoma cells." (PMID 27283490, 2017). "Knockdown of HDAC8 by RNA interference inhibits the proliferation of lung, colon, and cervical cancer cell lines, whereas up-regulation of HDAC8 promotes the proliferation and inhibits apoptosis in hepatocellular carcinoma." (PMID 28223544, 2017). "Also in hepatocellular carcinoma patients, HDAC8 expression significantly correlated with AHR transcription and protein levels." (PMID 37696456, 2023). "AhR factor stimulated the expression of HDAC8 via the AhR-ARNT complex in human hepatoma cells." (PMID 35987825, 2022). "In addition, HDAC8 inhibition significantly inhibited hepatoma cell proliferation and transformation activity via the upregulation of RB1 in vitro and in vivo." (PMID 34439391, 2021).
hepatocellular carcinoma (continued). "Furthermore, HDAC8 inhibition remarkably inhibited hepatoma cell proliferation and transformation activity via upregulation of RB1 in vitro and in vivo." (PMID 27283490, 2017). "Analyses of seven hepatoma cell lines (Hep G2, Hep 3B, SK-Hep1, Huh 7, PLC/PRF/5, HA22T, and HCC36) revealed that AHR and HDAC8 were highly expressed in all of the hepatoma cell lines as compared with expression levels in normal hepatocytes (Chang normal liver cells, CNL)." (PMID 27283490, 2017). "For example, in Nonalcoholic Fatty Liver Disease (NAFLD)-related Hepatocellular Carcinoma (HCC), HDAC8 and EZH2 regulated H4ac content and H3K27me3 levels of the AXIN2 gene, respectively." (PMID 39719443, 2024). "HDAC8 has been reported as an AHR target as it was induced by TCDD and by overexpression of AHR in hepatoma cell lines." (PMID 37696456, 2023). "Our data showed that the induction of AHR activated cellular expression of HDAC8 and consequently suppressed RB1 expression in hepatoma cells." (PMID 27283490, 2017). "Hepatoma cells with both AHR and HDAC8 expression showed an additive effect on cell proliferation activity." (PMID 27283490, 2017). "The hepatoma cells exhibiting both AHR and HDAC8 expression showed a more pronounced additive effect on transformation activity than that of AHR or HDAC8 alone." (PMID 27283490, 2017). "Downregulation of canonical Wnt pathway by PCI has been described in a model of hepatocellular cancer, in which HDAC8 physically interacts with chromatin modifier EZH2 to repress Wnt antagonists, activating Wnt pathway." (PMID 33015043, 2020). "Histone deacetylase 8 (HDAC8), a unique member of class I histone deacetylases, shows remarkable correlation with advanced disease stage and multiple malignant tumors However, little is known about the contribution of HDAC8 to the tumorigenesis of hepatocellular carcinoma (HCC)." (PMID 27283490, 2017). "Moreover, when hepatoma cells (SK-Hep1) were treated with TCDD, a prototypical AHR ligand, expressions of HDAC8 and the classical AHR target gene CYP1B1 were increased in hepatoma cells in a time-dependent manner, both at protein level." (PMID 27283490, 2017). "Similarly, CDX model intervention results indicated that the knockdown of HDAC8 significantly inhibited hepatocellular carcinoma growth in high‐palmitate diet‐fed mice, with or without the knockdown of ZDHHC12." (PMID 40787880, 2025). "To determine whether AHR activated HDAC8 via a genetic mechanism, we transfected an AHR expression construct into hepatoma cells, and the mRNA and protein levels of HDAC8 were measured by real-time PCR and western blotting, respectively, in AHR-overexpressing cells." (PMID 27283490, 2017). "However, opposite studies have shown that HDAC8 inhibition increases the expression of NKG2D ligand in glioma cells which enhanced the recognition ability and cytotoxicity of NK cells, and activates immune cells in hepatocellular carcinoma resulting in an effective and lasting response to ICB." (PMID 34880761, 2021). "Additionally, the long non-coding RNA (lncRNA) ID2-AS1, which downregulates inhibitor of DNA binding 2 (ID2), enhanced ID2 transcription by blocking HDAC8 occupancy at the ID2 enhancer region, thereby inhibiting hepatocellular carcinoma (HCC) invasion and migration both in vitro and in vivo." (PMID 40260239, 2025). "Given the important role of MPS1 and HDAC8 in hepatocellular carcinoma, the development of effective MPS1/HDAC8 inhibitors is a novel approach to cancer treatment." (PMID 39351092, 2024).